IL18 (interleukin 18)
Diseases named in the same sentence as IL18 in open-access papers (continued):
Sharing a sentence is not in itself a finding about the gene and the disease.
sarcoidosis (continued). "Compared to healthy donors, subjects with sarcoidosis had significantly higher levels of circulating IL-18, CXCL10, sIL-2R/CD25 and TNFR II, but not other tested cytokines." (PMID 38173720, 2023). "Our data showed measurable IL-18 both in BAL and serum of sarcoidosis patients." (PMID 36207373, 2022). "Treg numbers positively correlated with IL-18, sCD25, with TNFR II in plasma and with Ki-67+ in all PBMC subsets, suggesting that increased number of Tregs in sarcoidosis patients may reflect a compensatory effort of the immune system to control ongoing inflammation." (PMID 38173720, 2023).
bacteremia (16 papers, 2011 to 2025). "Excessive inflammasome activation–mediated IL-1β and IL-18 production is also reflective of monocyte/macrophage activation and has been associated with cytokine release syndromes, viral and bacterial sepsis, and autoinflammatory conditions." (PMID 33232303, 2021). "IL18RAP is a subunit of the heterodimeric receptor for interleukin 18 and is reported to be elevated in E. coli-caused bacteremia." (PMID 31093495, 2019). "When IL-18 was given to septic mice to mimic the human condition, mortality was dramatically increased compared to septic mice alone and was associated with increased bacteremia, intestinal injury, and an increased systemic inflammatory response predominated by IL-17A." (PMID 28224121, 2017). "LIGHT levels in bacterial sepsis and IL-18 levels in both bacterial and viral sepsis were positively correlated with TNFR2." (PMID 35203474, 2022). "PAI-1 levels show a significant correlation with ARDS and AHRF, which are also positively correlated with LIGHT levels in bacterial sepsis and positively correlated with IL-18 levels in both bacterial and viral sepsis." (PMID 35203474, 2022). "We observed a wide dynamic range of IL-18 plasma concentrations, from 80 to >32,400 pg/mL in bacterial sepsis, and from 161 to 19,100 pg/mL in viral sepsis." (PMID 35203474, 2022). "We found, in comparison to healthy controls, that patients with SAB generally displayed higher caspase‐1 activity in both neutrophils and monocytes during the first week of bacteremia, as well as elevated plasma levels of the proinflammatory cytokine IL‐18." (PMID 31403210, 2019). "We found induced caspase‐1 activity in innate immune cells with subsequent release of IL‐18 in patients during the acute phase of bacteremia, indicating activation of the inflammasome." (PMID 31403210, 2019). "While pyroptosis has a clear impact on infection, the cytokines IL-1β and IL-18 appear to play minor roles in the control of the bacteria, since IL-1β and IL-18-deficent mice show little delay in bacteremia at 72 h." (PMID 24381573, 2013). "While no study has assessed IL-18 secretion in human LD, several studies have shown that high plasma IL-18 levels are associated with poor clinical outcome in patients with bacterial sepsis." (PMID 37965258, 2023). "Furthermore, there was a large interindividual difference in both caspase‐1 activity and plasma levels of IL‐18 among patients with bacteremia." (PMID 31403210, 2019). "Early response cytokines (i.e. first wave at initiation of bacteremia) included IFN-γ, IL-1β, IL-6, IL-18, IL-1ra, IL-10, IL-12 (p40), IL-17a and MCP-1, which all reached peak levels during bacteremia." (PMID 35925895, 2022). "In addition, the correlation of IL-18 with Apache III scores, mortality, and AKI was consistently observed in both bacterial sepsis and viral sepsis." (PMID 35203474, 2022).
familial Mediterranean fever (16 papers, 2018 to 2026). Familial Mediterranean fever (FMF) is an autoinflammatory disorder characterized by recurrent short episodes of fever and serositis resulting in pain in the abdomen, chest, joints and muscles. "Familial Mediterranean fever is caused by mutations of MEFV that increase the release of the inflammatory cytokines IL-1 and IL-18, resulting in systemic inflammation, and vasculitis in particular." (PMID 39403923, 2024). "It should be born in mind, that patients with INC displayed elevated levels of Il1β, Il18, and caspase 1 compared to healthy controls, but they also displayed significantly elevated levels of Il18 compared to patients with Familial Mediterranean Fever, a prototypical autoinflammatory disease." (PMID 35011732, 2022). "Autoinflammatory diseases, such as tumor necrosis factor receptor‐associated periodic syndrome (TRAPS) and familial mediterranean fever (FMF), have all been directly linked with excessive production of IL‐1β and IL‐18,14 because of heightened inflammasome responses." (PMID 35832835, 2022). "Serum IL-18 levels were significantly elevated in some patients with familial Mediterranean fever (FMF), although they were not significantly elevated in most patients with FMF." (PMID 36211331, 2022). "In familial Mediterranean fever (FMF), ex vivo LPS-stimulated PBMCs and monocytes produce more IL-1α and β, IL-6, IL-8, IL-12, IL-18, and TNFα, and in non-stimulated PBMCs higher production of IL-6 and TNFα was found, and also expression of CD11b was increased." (PMID 29515591, 2018).
cognitive decline (15 papers, 2011 to 2025). "Blocking NLRP3 inflammasome activation with siNlrp3 or MCC950 reduced interleukin-1β and interleukin-18 production, thereby effectively mitigating cognitive decline, locomotor behavior impairment, and neurodegeneration in TX mice." (PMID 33462188, 2021). "Taken together, the elevated levels of angiopoietin-2, Serpin E1, uPAR, and IL-18 may promote chronic inflammation, blood–brain barrier dysfunction, and neuronal damage, contributing to the neuroinflammation and cognitive decline characteristic of SZ." (PMID 39940697, 2025). "IL-18, a member of IL-1 family, was elevated in LPS-stimulated blood mononuclear cells and brains of AD patients, and a significant correlation between IL-18 production and cognitive decline was observed." (PMID 27054030, 2016). "IL-1β and IL-18 are elevated in the AD brain and have been hypothesized to contribute to neurodegeneration and cognitive decline in AD." (PMID 22824372, 2012). "Further studies are needed to determine whether the NLRP1 inflammasome-induced activation and increased IL-1β and IL-18 observed in our study influence deficits in synaptic transmission leading to cognitive decline." (PMID 22133203, 2011). "The cognitive decline in the aging process is regulated by the increased expression of caspase-1, a protein that regulates the maturation and secretion of interleukin (IL)-1β and IL-18, and decreased expression of BDNF, a protein that improves synaptic connectivity." (PMID 34526890, 2021). "Thus, aging processes stimulate activation of the NLRP1 inflammasome and secretion of IL-1β and IL-18 that may contribute to age-related cognitive decline in the growing elderly population." (PMID 22133203, 2011). "Six genes were associated with frailty and cognitive decline in Sargent’s recent review: IL-6 rs1800796, TNF rs1800629, IL-18 rs360722, IL1-beta rs16944, and COMT rs4680 for cognitive decline and COMT rs4646316 for frailty." (PMID 32257550, 2020).
dementia (15 papers, 2010 to 2026). Loss of intellectual abilities interfering with an individual's social and occupational functions. "Overall, these data indicate that IL-18-related inflammatory pathways, are exacerbated in the peripheral blood of AD patients, and that this cytokine may indeed participate in pathogenic processes leading to dementia." (PMID 20113500, 2010). "IL-18 and epidermal growth factor levels were higher in Black individuals with a parental history of dementia compared to Hispanic individuals with the same history." (PMID 41968642, 2026). "It has been found that the levels of inflammation-related markers, such as IL-1β, IL-18, and IL-6, are increased in both DM and dementia patients." (PMID 32425784, 2020). "Our findings also covered well-known dementia-associated proteins, such as BCAN, CNTN5, and NCAN, along with identifying recently promising biomarkers, including IL18, MMP12, TNFSF12, and UNC5C, where these biomarkers presented the highest protein importance in their clusters." (PMID 40748327, 2025). "In support of this mechanism, evidence from a growing number of longitudinal studies suggests that markers of systematic inflammation, such as tumor necrosis factor, nitric oxide synthase, and interleukin IL-1β, IL-6, and IL-18, are involved in the pathogenesis of dementia." (PMID 32651320, 2020). "Moreover, endogenous IL-18 neutralization with anti–IL-18 IgG inhibits cytokine production and NF-κB activation in rat model of vascular injury, suggesting its potential for the treatment of dementia of vascular origin." (PMID 38659577, 2024). "In previous studies, elevated peripheral vascular cell adhesion molecule-1, tumor necrosis factor (TNF)-α, IL-2, IL-6, IL-18, and interferon-γ were found in patients with mild AD, suggesting that cytokine signaling might play a role in the intermediate stages of dementia." (PMID 35069588, 2021). "Furthermore, these findings support the recently hypothesized participation of IL-18 in the progressive neurodegeneration that occurs in some forms of dementia." (PMID 22642744, 2012). "Finally, it has been hypothesized that increased production of IL-18 in the brain may lead to motor and cognitive dysfunctions, leading to the development of HIV-associated dementia." (PMID 20113500, 2010). "Our study highlights the changes and potential contributions of several chemokines (CXCL1, CCL3, CXCL5, CXCL6, CCL3, CCL19), interleukins (IL8, IL6-RA, IL18-BP), and other immune markers (OSM, ALCAM, OPG, CHIT1, YKL-40, STAMBP, MMP-9, MMP-10) in the prodromal and dementia phases of AD." (PMID 31694701, 2019).
myocardial ischemia (15 papers, 2015 to 2024). A disorder of cardiac function caused by insufficient blood flow to the muscle tissue of the heart. "The effect of sevoflurane on myocardial ischemia has been shown in both in vivo and in vitro models, and is associated with anti-inflammation and the inhibition of inflammasomes, IL-1β, IL-18, and cell pyroptosis." (PMID 39202513, 2024). "IL-1β and IL-18 both belong to the IL-1 superfamily and recent evidence shows that IL-1β activates IL-18 in the course of myocardial ischemia/reperfusion injury and acute heart failure." (PMID 31247004, 2019). "In the treatment of rats, a model of myocardial ischemia, the alcoholic extract of Tiekuaizi reduced the expressions of interleukin-18 (IL-18), interleukin-6 (IL-6), and TNF-α and was able to protect against myocardial cell injury produced by inflammatory cell infiltration." (PMID 39830344, 2024). "In addition, besides implications for plaque instability, IL-18 has been recently discovered to be involved in myocardial ischemia-reperfusion injury." (PMID 26669254, 2015). "It is also reported to attenuate myocardial ischemia–reperfusion by regulating the PI3K/Akt signaling pathway and the subsequent reduction of inflammatory factors, including IL-6, IL-18, and TNF-α." (PMID 28529539, 2017).
polycystic ovary syndrome (15 papers, 2010 to 2025). A disorder that manifests as multiple cysts on the ovaries. "Several studies have addressed the association between IL-18 levels in serum and polycystic ovaries." (PMID 27747236, 2016). "Polycystic ovary syndrome is associated with a marked increase in inflammation biomarkers such as C-reactive protein (CRP), IL-18, and MCP-1, and is also associated with other inflammation-related disorders." (PMID 39768981, 2024). "Recent research shows that polycystic ovary syndrome (PCOS) may have an association with low-grade chronic inflammation, and that PCOS may induce an increase in serum interleukin-18 (IL-18) levels." (PMID 20964873, 2010). "Recent research show that polycystic ovary syndrome (PCOS) may have an association with low-grade chronic inflammation, IL-18 is considered as a strong risk marker of inflammation." (PMID 21244650, 2011). "Studies have indicated that individuals with polycystic ovary syndrome exhibit elevated levels of inflammatory markers such as TNF, IL-6, CRP, IL-18, IL-1β, and white blood cell counts." (PMID 40933264, 2025). "In women with polycystic ovary syndrome (PCOS), their GCs and follicular fluid have higher levels of IL18 transcript and IL18 protein, respectively, implying involvement of this agent in the pathogenesis of these ovarian dysfunctions." (PMID 39468655, 2024). "Increased levels of the inflammatory cytokines Il-6 (interleukin-6), Il-18 (interleukin-18), TNF-alpha (tumor necrosis factor alpha), hsCRP (high-sensitivity C-reactive protein) and ferritin are present in patients with polycystic ovary syndrome." (PMID 37509592, 2023). "MT promotes the expression levels of CYP19A1 and HO-1 in human ovarian GCS, reduces the level of IL-18, and promotes the oocyte maturation in PCOS patients with hyperandrogenemia." (PMID 34228638, 2021).
preeclampsia (15 papers, 2010 to 2025). Preeclampsia is a hypertensive disorder of pregnancy that is characterized by new-onset hypertension with proteinuria presenting after 20 weeks of gestation, and depending on mild or severe forms may initially present with severe headache, visual disturbances, and hyperreflexia. "Elevated IL-18 levels are linked with preeclampsia and IUGR." (PMID 41394354, 2025). "IL-18 concentrations in the second trimester are higher in women who develop preeclampsia compared to controls." (PMID 33680514, 2021). "Recent studies have demonstrated that urinary KIM-1 and IL-18 are potential biomarkers of early-stage AKI caused by contrast-induced nephrotoxicity, cardiac surgery, and preeclampsia, and can reveal AKI much earlier than canScr." (PMID 26283194, 2015). "Patients with AKI as a complication of preeclampsia, contrast-induced nephropathy, and coronary angiography have significant increases in urinary IL-18 prior to the occurrence of increases in Scr and serum BUN." (PMID 26283194, 2015). "Recently study showed that increased serum level of IL-18 was observed in preeclampsia, premature rupture of membranes, acute fatty liver of pregnancy and fetal growth restriction." (PMID 21244650, 2011). "Studies on pre-eclampsia, objectify an increase of IL-18 in serum and placenta compared to control healthy women, probably as part of the exacerbated inflammatory response that is part of the pathogenesis of preeclampsia." (PMID 37373945, 2023). "Serum and placental levels of pro-inflammatory IL-18 are increased in preeclampsia." (PMID 26247971, 2015). "Research suggests that IL-12p40, IL-12p70, IL-17, IL-18, and TGF-β are elevated in women with preeclampsia in the third trimester compared to healthy controls." (PMID 33680514, 2021).
steatosis (15 papers, 2018 to 2025). Increased lipid within the cytoplasm of cells. "Mice with hepatocyte-specific CD147 deletion exhibited attenuated NASH phenotypes, including reduced steatosis, liver injury, hepatocyte apoptosis and inflammatory cytokines IL-1β/IL-18 secretion." (PMID 32903542, 2020). "In contrast, elevated IL-18 can reflect degree of steatosis in addition to inflammation and therefore can be recognized as more representative for complexity of NAFLD pathogenesis." (PMID 29854715, 2018). "Finally, a role for altered gut microbiota composition has been advanced to explain steatosis in IL-18-/- mice." (PMID 36313762, 2022). "IL-18 is a proinflammatory cytokine that can be produced by adipocytes, macrophages, Kupffer cells, and endothelial cells, and increased IL-18 can reflect the degree of inflammation and steatosis." (PMID 35782337, 2022). "Moreover we analyzed effect of steatosis degree on serum IL-18 levels to establish its possible predictive role for the disease progression in comparison to several other markers of hepatic injury, metabolic dysfunction, and systemic inflammation." (PMID 29854715, 2018). "Interestingly elevated IL-18 was accompanied by higher activities of hepatocyte injury enzymes in more advanced steatosis irrespective of diagnostic method with USG or 1HMRS." (PMID 29854715, 2018). "Markedly higher levels of pro-inflammatory cytokines and chemokine, including TNF-α, IL-6, IL-18, and MCP-1 were detected in NASH serum than in those from the Non-steatosis group." (PMID 36209205, 2022). "Firstly, the palmitate acid-induced hepatocytes steatosis involved the activation of NLRP3 inflammasome and increased secretion of IL-1β and IL-18." (PMID 32477116, 2020). "Patients with steatosis in USG and elevated ALT demonstrated significantly higher IL-18 activity than those with steatosis but normal ALT (310 versus 339 pg/mL; p = 0.044)." (PMID 29854715, 2018). "In addition, HLF increased the activities of plasma SOD, CAT, and GSH-Px and decreased the levels of Casp 1, NLRP3, IL-1β, IL-18, and TNF-α, improving the degree of hepatocyte steatosis and inflammatory infiltration of rats." (PMID 36425260, 2022). "Therefore, the inflammatory cytokines TNF-α, IL-1β, and IL-18 may combine with CXCL1 to synergistically induce liver injury and steatosis." (PMID 40606614, 2025). "Ketone bodies, particularly β-hydroxybutyrate, have been associated with inflammasome inhibition and IL-18 production; the MCN map implies an indirect negative correlation with fibrosis, which is consistent with non-alcoholic steatosis-related patterns of fibrosis." (PMID 37623872, 2023). "Likewise, given that the presence of inflammation differentiates NASH from steatosis, further studies comparing serum levels of ASC, IL-18, and Gal-3 in patients with NASH to those with steatosis may help validate these potential biomarkers for NASH." (PMID 33203036, 2020). "This is in line with results from the study of Vecchiet at al. who demonstrated higher IL-18 in NAFLD adult patients compared to controls but lower IL-18 than in patients with chronic hepatitis C, indicating possible role of hepatic inflammation in addition to steatosis regarding IL-18 production." (PMID 29854715, 2018).